IL1B (interleukin 1 beta)
Diseases named in the same sentence as IL1B in open-access papers (continued):
Sharing a sentence is not in itself a finding about the gene and the disease.
Sepsis (continued). "The overwhelming production of proinflammatory cytokines, such as interleukin (IL)-1β, IL-6, tumor necrosis factor (TNF)-α, as well as reactive oxygen species (ROS) is a hallmark of sepsis and sepsis-associated AKI." (PMID 40656894, 2025). "In advanced sepsis cardiac dysfunction, inflammatory cytokines (IL-1β, TNF-α) activated by increasing the inducible nitric oxide synthase (iNOS), which further sustains the production of excess NO." (PMID 40356926, 2025). "Serine plays a crucial role in the LPS‐induced expression of IL‐1β mRNA expression and inhibiting de novo serine synthesis in vivo reduces LPS‐induced IL‐1β levels while improving survival in a mouse sepsis model." (PMID 40276648, 2025). "In this scenario, proinflammatory cytokines, such as TNF-α, IL-1β, and IL-6, have been confirmed to act in the acute phase of sepsis, mediating the systemic response and progression to multiorgan dysfunction." (PMID 41268545, 2025). "Renal concentrations of TNF‐α, IL‐6, and IL‐1β were assessed in the Sham, sepsis and Cur + Sep groups." (PMID 41140036, 2025). "In the sepsis model, MP-10 significantly reduced inflammation, decreased plasma IL-1β, alleviated thrombocytopenia, and improved organ damage markers." (PMID 40429643, 2025). "Even though an extended panel of cytokines has been proposed to participate in sepsis, IL-1β and TNF-α appear to be representative of the two basic mechanisms, namely inhibition of pathogens and tissue damage minimization." (PMID 40142568, 2025). "GeneWalk analysis identified potential regulatory genes involved in sepsis, including IL1B, CDKN1A, CDK2, CSF3, and IL1R2, which were included among the SRGs." (PMID 40303348, 2025). "The inflammatory environment in septic patients is highly complex, involving a combination of pro-inflammatory cytokines associated with the systemic inflammatory response characteristic of sepsis (e.g., IL-1β, IL-6, TNF-α, and interferon-γ)." (PMID 40950553, 2025). "Up to our knowledge, the stronger effect on the gene expression of the pro-inflammatory cytokines IL-1b and IL-6 through ASCs compared to BMMSCs at the early (8 h) onset of sepsis is a new finding." (PMID 40253667, 2025). "The initiation of the inflammatory response plays a vital role in SIMI, triggering the release of numerous pro-inflammatory factors such as TNF-α, IL-6, and IL-1β during sepsis." (PMID 40458798, 2025). "Our analysis of the dataset (GSE225192) revealed that, compared with the sham group, mRNA levels of TIFA and IL-1β were significantly elevated in sepsis." (PMID 40385253, 2025). "In animal studies, MitoTempol has been shown to reduce levels of the inflammatory marker IL-1β, lower oxidative stress in the kidneys, and improve kidney function in the context of sepsis." (PMID 40546532, 2025). "Pharmacological inhibition or genetic deletion of P2X7 receptor attenuates the production of IL-1β, reduces neuroinflammation and prevents cognitive impairments in sepsis-surviving animals." (PMID 40713568, 2025). "Sepsis is defined by the impairment of the immune system, which is closely linked to an overabundance of proinflammatory cytokines like TNF-α, IL-1β, and IL-6." (PMID 40144662, 2025). "Our study also demonstrated substantially elevated levels of IL-1β and IL-18 in critically ill patients—including those with sepsis—compared to healthy adult and pediatric controls." (PMID 40722817, 2025). "Key cytokines involved in sepsis, such as IL-1β, were excluded from our analysis, as its bioactive form cannot be detected through intracellular staining." (PMID 40178612, 2025). "IL-1β levels in the kidney tissue were significantly elevated in the sepsis group and all TCZ-treated groups compared to the healthy group." (PMID 39955435, 2025). "We observed a myocardial upregulation in expression of inflammatory cytokines IL-1β and IL-6 along with increased macrophage staining, which was more pronounced in acute than in prolonged sepsis." (PMID 39821755, 2025).
Sepsis (continued). "This nanosystem showed potential in downregulating the levels of inflammasome components such as NLRP3, caspase‐1, and IL‐1β, suggesting its ability to modulate inflammasome activation in sepsis‐induced lung injury." (PMID 40599085, 2025). "In prolonged sepsis, cardiac expression of IL-1β and IL-6 and macrophage infiltration remained upregulated (p ≤ 0.05)." (PMID 39821755, 2025). "Sepsis is a critical illness caused by infection that leads to excessive activation of systemic inflammatory cytokines, such as TNF-α, IL-1β, and IL-6, inducing immune dysfunction and resulting in systemic organ failure." (PMID 40565375, 2025). "TNFα and IL1β are pro-inflammatory cytokines involved in several disease and conditions including sepsis and tumor invasion, and both cytokines induce degradation of the EC barrier and expression of adhesion molecules." (PMID 39761260, 2025). "In sepsis, inflammatory mediators such as cytokines (TNFα, IL-1β) and NO lead to thr dysregulation of calcium release from the sarcoplasmic reticulum (SR)." (PMID 39941634, 2025). "Research has shown that IL-1β levels are typically elevated in sepsis patients, and its levels are positively correlated with the severity of SAKI." (PMID 40166075, 2025). "Our group has demonstrated elevated hippocampal IL-1β levels during the acute phase of sepsis in senescence-accelerated mice, suggesting a role for the NLRP3-IL-1β pathway in the chronicity of SAE." (PMID 40556654, 2025). "During sepsis, exosomes contribute to the progression of inflammation by carrying proinflammatory cytokines (such as IL-1β, IL-6, TNF-α) and activating Toll-like receptors (TLR2, TLR4, TLR7) in immune cells." (PMID 41268545, 2025). "We found that Areg, Egfr, Il1b, and Il18 were highly expressed in monocytes of patients with severe sepsis compared with those in patients with general sepsis or healthy controls." (PMID 40292295, 2025). "Compounds such as baicalin, cortistatin, and sulfur dioxide have been reported to inhibit NLRP3 activation, reduce IL-1β and IL-18 levels, and mitigate oxidative stress and cell death in animal models of sepsis." (PMID 40558557, 2025). "Inflammatory mediators that are commonly elevated during the acute phase of sepsis include interleukins (IL)-1β, IL-6, IL-8, CC motif chemokine ligand 2 (CCL2) and tumour necrosis factor (TNF)-α." (PMID 41124072, 2025). "In a murine sepsis model, we identified a subset of lung-resident macrophages characterized by robust IL-1β expression as pivotal contributors to lung damage." (PMID 41360768, 2025). "In the ELISA, CBD treatment indicated the downregulation of TNF-α, IL-6, and IL-1β expression levels in the serum samples of the LPS-mediated sepsis mouse models." (PMID 41465451, 2025). "In the low-dose levosimendan group, IL-1β levels were significantly elevated at the 5th hour, exceeding those observed in both the sham and sepsis control groups." (PMID 40566580, 2025). "Interleukins are produced by many WBCs and are involved in the differentiation and activation of other immune cells, with IL-1β, IL-6, and IL-10 being the most studied in the context of sepsis." (PMID 39968295, 2025). "During sepsis, several chemokines and inflammatory cytokines are involved including IL-1B, IL-6, IL-12, and IL-7." (PMID 40546532, 2025). "In the hippocampus of septic mice, several data reports suggest that significantly higher levels of IL-1β 24 hours after sepsis." (PMID 39473252, 2025). "In sepsis animal models treated with autophagy activators, the concentrations of inflammatory cytokines such as IL-1β and TNF-α in the serum can increase several times or even more compared to the untreated group." (PMID 40766066, 2025). "Systemic inflammation was assessed by measuring TNF-α, IL-1β, IL-6, and MCP-1, which are hallmark inflammatory mediators of sepsis." (PMID 40185975, 2025).
Sepsis (continued). "Protein interaction network analysis revealed interleukin (IL) 1 beta (β) as central player in sepsis-related brain alterations, supporting previous research linking IL1β to cognitive dysfunction." (PMID 40303348, 2025). "ZIP8 not only suppresses NF-κB signaling through zinc-dependent inhibition of IκB kinase (IKK), but also promotes IL-1β production and ferroptosis in sepsis." (PMID 41583444, 2025). "We investigated possible IL1B+macrophages and CD14+ monocyte pathways since systemic IBD and Sepsis are associated with enhanced cell ratios and pronounced hub gene expression." (PMID 39993996, 2025). "ELISA was used to measure systemic inflammatory responses in sepsis model rats by determining concentrations of serum IL-6, IL-1β and TNF-α." (PMID 40582762, 2025). "IL-17 (also known as IL-17A) is produced by IL-23-stimulated Th17 T cells after sepsis and induces the synthesis of various cytokines such as IL-1β, IL-6, and TNF-α." (PMID 40520010, 2025). "Comparative analysis across diagnostic categories revealed that patients with sepsis exhibited significantly elevated levels of RIPK-1, IL-1β, and IL-18, along with reduced caspase-8 levels, relative to patients with SIRS or cardiac conditions." (PMID 40722817, 2025). "The elevation in IL-1β levels was lower in the TCZ1 group compared to the sepsis group and the other TCZ treatment groups." (PMID 39955435, 2025). "To confirm the anti-inflammatory activity of CBD in LPS-induced sepsis mouse model, we investigated the protein expression levels of inflammatory cytokines, such as TNF-α, IL-6, and IL-1β from the sepsis mouse serum samples." (PMID 41465451, 2025). "Compared with those in Gsdmdfl/fl mice, improved survival and significantly decreased plasma IL-1β concentrations were observed in Gsdmdfl/flAlbCre/+ mice with sepsis, and these effects were reversed by rHMGB1 protein injection." (PMID 39927458, 2025). "JKAP is also lower in sepsis patients and is inversely associated with levels of TNF-α, IL-1β, and IL-17 and disease severity-related scales." (PMID 41458980, 2025). "Promising experimental evidence has shown that curcumin protects cardiomyocytes from sepsis-induced injury by activating the Nrf2/HO-1 pathway, mitigating ferroptosis, and attenuating the IL-6 and IL-1β response to LPS stimulation." (PMID 41300951, 2025). "Mitochondrial transplantation conducted one hour after CLP showed a tendency towards reducing TNF-α, IL-1β, and IL-6 levels compared to the Sepsis group." (PMID 40584438, 2025). "IL-1β levels in the lung tissue were significantly elevated in the sepsis group compared to the healthy group." (PMID 39955435, 2025). "The NLRP3 inflammasome activation is a tightly controlled process that regulates the release of the powerful pro-inflammatory cytokine IL-1β in sepsis." (PMID 40086696, 2025). "In a mouse sepsis model, disulfide effectively reduced mortality and decreased the levels of inflammatory cytokines such as IL-1β, TNF, and IL-6 in serum." (PMID 41041277, 2025). "The activation of the NLRP3 inflammasome is implicated in the pathogenesis of various inflammatory conditions, for example sepsis, leading to significant elevations in IL-1β, IL-18, and caspase-1 levels." (PMID 40918153, 2025). "In the initial stage of sepsis, the release of a large number of pro-inflammatory cytokines including TNF-α and IL-1β are associated with intestinal barrier impairment." (PMID 40885907, 2025). "of sepsis induction revealed an exacerbated inflammatory response evidenced by increased tissue levels of proinflammatory cytokines IL‐6, IL‐1β and TNF‐α." (PMID 39444093, 2025). "For instance, in a mouse model of cardiac dysfunction induced by sepsis, pre-treatment with losartan reversed the increase in IL-1β, IL-6, TNF-α, and MCP-1." (PMID 40647187, 2025). "Angiotensin II among other factors stimulate macrophage activity, with IL-1β playing a central role in the inflammatory process in sepsis-induced cardiac issues." (PMID 40458798, 2025).
Sepsis (continued). "In the early phase of sepsis, innate immune responses stimulate platelet activation through toll-like receptors, leading to interleukin-1β (IL-1β) release and the formation of neutrophil extracellular traps that help contain pathogens." (PMID 40723124, 2025). "The initiation of NF-κB activation is controlled by the phosphorylation of IκB-α, leading to its degradation and, consequently, upregulation of inflammatory cytokines, including TNF-α, IL-1β, and IL-6, which are considered hallmarks of sepsis." (PMID 39940359, 2025). "IL-1β concentrations in the sepsis control group increased progressively, with a statistically significant elevation at the 10th hour relative to the sham group." (PMID 40566580, 2025). "Arg1 inhibition in monocytes abolished the protective effects of exercise on reducing body temperature decline, weight loss, IL-1β and TNF-α levels and sepsis-induced myocardial injury." (PMID 41398160, 2025). "Some findings are consistent with our study, for instance, IL17A, IL1B, MBL, NOD2, PPARG and SOD2 genes were associated with sepsis." (PMID 40168842, 2025). "IL-1β levels were significantly elevated in all three patient groups—sepsis, SIRS, and cardiac—compared to healthy controls, with similar distributions observed in both adults and children." (PMID 40722817, 2025). "The study authors demonstrated that pro-inflammatory cytokines, namely IL-1b and IL-6, were down-regulated in mice with sepsis-induced ALI by miR-483-5p knockdown." (PMID 40076471, 2025). "The pathogenesis of sepsis involves the initial excessive activation of the immune system, resulting in the release of pro-inflammatory cytokines such as Interleukin-1 beta (IL-1β), Interleukin-6 (IL-6) and Tumor Necrosis Factor-alpha (TNF-α)." (PMID 40688672, 2025). "Effective management of sepsis, therefore, often focuses on controlling the levels of IL-1β to mitigate its harmful effects." (PMID 40667510, 2025). "IL-1β is a critical mediator in the pathophysiology of sepsis, significantly contributing to the disease’s progression and severity." (PMID 40667510, 2025). "A study by Liu (2010) examining dynamic changes in circulatory cytokine and chemokine levels during the early phase of sepsis also found a significant positive correlation between IL-1β and IL-2." (PMID 40283868, 2025). "ILs such as IL-1β, IL-6, IL-12, IL-17 and IL-18 play a crucial role in sepsis-induced myocardial injury." (PMID 40520010, 2025). "Lowers TNF-α and IL-1β serum levels, serves as a diagnostic and prognostic tool, and neutralizes TREM-1 while activating monocytes in sepsis patients." (PMID 41226426, 2025). "The reduction in the TNF-α and IL-1b by MXF exhibits its protective properties in sepsis and protects the organ damage." (PMID 40327662, 2025). "Studies on sepsis suggest that IL-1β is among the first inflammatory factors to increase and plays a crucial role in neurological dysfunction by mediating the entry of inflammatory mediators into the brain." (PMID 40666186, 2025). "This study reveals a novel immune-metabolic axis whereby IL-1β+ macrophages orchestrate endothelial dysfunction and tissue injury in sepsis." (PMID 41360768, 2025). "Compared with those of the DMSO-treated mice, the rHMGB1 protein–induced lung edema, lung microvascular permeability, aortic permeability, and plasma IL-1β levels of the WT mice with sepsis were obviously reversed by FPS-ZM1." (PMID 39927458, 2025). "We conclude that IL1B+ macrophages expressing high levels of these hub genes play a key role in the immune dysregulation associated with both IBD and Sepsis." (PMID 39993996, 2025). "Experimental models demonstrate that silencing AIM2 or its downstream effectors significantly reduces IL-1β levels and mitigates tissue damage, highlighting its potential as a therapeutic target in sepsis." (PMID 40558557, 2025).
Sepsis (continued). "Proinflammatory cytokines, such as TNF-α and IL-1β, released during sepsis indirectly suppress the activity of the PI3K catalytic subunit p110 via activation of the nuclear factor kappa B (NF-κB) pathway." (PMID 40823184, 2025). "Inhibition via C75 furthermore blocks IL‐1β secretion in murine macrophages in the context of sepsis." (PMID 41416928, 2025). "These cytokines play a crucial role in sepsis, with IL-1β and TNF-α being pro-inflammatory factors that exacerbate systemic inflammation, while IL-6 is closely involved in the acute-phase response and immune modulation." (PMID 40422869, 2025). "Monocyte transfusion significantly alleviated the drop in body temperature and body weight, as well as reduced IL-1β and TNF-α production caused by sepsis." (PMID 41398160, 2025). "Since excessive inflammation plays a vital role in the pathogenesis of sepsis-associated cardiac abnormalities, we measured the levels of inflammatory cytokines TNF-α and IL-1β." (PMID 41311552, 2025). "This immunomodulatory effect of DEX was also observed in a CLP mouse model, in which DEX-treated sepsis mice had significantly lower concentrations of IL-6 and IL-1β in the blood and hippocampus." (PMID 41124072, 2025). "Increased glycolysis and inflammasome-dependent upregulation of inflammasome NLRP3, involved in the maturation and release of IL-1β, an essential cytokine of sepsis-induced inflammation, are enhanced by mitochondrial inhibition." (PMID 41488672, 2025). "Sepsis is a systemic inflammatory response triggered by infection, characterized by the overproduction of pro-inflammatory cytokines (e.g., IL-1β, IL-6, TNF-α), which ultimately leads to cytokine storm and multiple organ dysfunction syndrome (MODS)." (PMID 40877572, 2025). "In the mouse model of sepsis, inhibition of caspase-1 can provide neuroprotection by reducing microglial activation and attenuating serum and brain expression of IL-1β and TNF-α." (PMID 39473252, 2025). "Compared with the vehicle, the GSDMD activation inhibitor obviously reduced the mortality rate and plasma HMGB1 and IL-1β concentrations in the mice with sepsis." (PMID 39927458, 2025). "The combined effects of ROS, IL-1β, and cytokines increase capillary permeability, hypoperfusion, and hypotension—defining features of advanced sepsis." (PMID 40558557, 2025). "IMD1 − 53 provide protection against heart injury and inflammation by attenuating the NLRP3/Caspase-1/IL-1β pathway during sepsis." (PMID 38616256, 2024). "The present study focuses on the mechanisms by which interleukin 1 β (IL-1β), as a critical mediator of sepsis-induced cholestasis, controls the expression of BSEP in hepatocytes." (PMID 39680527, 2024). "Sepsis induces an up-regulation in the production of proinflammatory cytokines, including IL1-β, IL-6, and TNF-α." (PMID 38629103, 2024). "Specific pro-inflammatory cytokines, including IL-1β, CCL4, CCL5, and CXCL10, have emerged as potential diagnostic markers for sepsis and critical indicators of cytokine storm severity." (PMID 38496165, 2024). "Dunnett's multiple comparisons test showed that sepsis significantly increased IL‐1β expression in the hippocampal tissues of septic mice (p < 0.001)." (PMID 39370294, 2024). "IL-1β gene expression was significantly higher in foals with naturally-occurring sepsis than foals with neonatal maladjustment syndrome." (PMID 39273060, 2024). "In recent years, an increasing number of biomarkers, including CRP, PCT, and IL-1β, are being utilized in clinical settings to enhance, have been explored for their potential to improve the predictive accuracy of sepsis prognosis." (PMID 39850096, 2024). "Various miRNAs, such as mi146a, are upregulated in the murine sepsis models and concentrated into EVs upon IL-1β treatment." (PMID 38922501, 2024). "Sepsis is characterized by an inflammatory response triggered by infections, leading to the release of proinflammatory cytokines such as interleukin-1beta (IL-1β), IL-6, and TNF-α." (PMID 38629103, 2024).